MCHR1 (melanin concentrating hormone receptor 1)
Description:
G protein-coupled receptor for melanin-concentrating hormone (MCH) that signals primarily through G(i/o) to inhibit adenylyl cyclase, and can additionally couple to G(q/11) to stimulate phospholipase C and mobilize intracellular calcium. Predominantly localized within the central nervous system where it regulates various physiological processes including feeding behavior, energy homeostasis, stress/anxiety-related behaviors and sleep.
Synonyms: MCH1R; GPR24; SLC1; MCH-1R; SLC-1
Tractability: Small molecule: a structure with a bound ligand is known; a high-quality ligand is known; it belongs to a druggable protein family. Antibody: UniProt places it where antibodies can reach, with high confidence; its Gene Ontology location is reachable by antibodies, with high confidence; UniProt predicts a signal peptide or a membrane-spanning region. PROTAC: a small molecule that binds it is known.
Target class: Peptide receptor (family A GPCR); Short peptide receptor (family A GPCR); MCH receptor; Family A G protein-coupled receptor; Membrane receptor
Chemical probes: CHEMBL570296, T-71
Gene: Protein-coding gene on chromosome 22 (40,679,273 to 40,682,812, forward strand). Ensembl gene ENSG00000128285.
Subcellular location: Cell membrane
Pathways (Reactome):
Signal Transduction: G alpha (i) signalling events; G alpha (q) signalling events; Peptide ligand-binding receptors
Organelle biogenesis and maintenance: BBSome-mediated cargo-targeting to cilium
Gene Ontology:
Molecular function: melanin-concentrating hormone receptor activity; protein binding; G protein-coupled receptor activity; neuropeptide binding; neuropeptide receptor activity; hormone binding; signaling receptor binding
Biological process: adenylate cyclase-inhibiting G protein-coupled receptor signaling pathway; phospholipase C-activating G protein-coupled receptor signaling pathway; energy homeostasis; feeding behavior; G protein-coupled receptor signaling pathway; generation of precursor metabolites and energy; neuropeptide signaling pathway; positive regulation of cytosolic calcium ion concentration; regulation of feeding behavior; response to stress; sleep; cell surface receptor signaling pathway; positive regulation of calcium ion transport
Cellular component: cilium; plasma membrane; neuron projection; non-motile cilium; 9+0 non-motile cilium; ciliary membrane; membrane
Genetic constraint (gnomAD): Loss-of-function variants: 13 observed, 21.77 expected, observed/expected ratio (o/e) 0.6, 90% interval 0.39 to 0.95. The upper end of that interval is the gene's LOEUF score, 0.95, which puts it in group 4 of 6, group 1 being the genes least tolerant of losing a copy. Missense variants: 472 observed, 498.75 expected, observed/expected ratio (o/e) 0.95, 90% interval 0.88 to 1.02. Synonymous variants: 215 observed, 213.97 expected, observed/expected ratio (o/e) 1, 90% interval 0.9 to 1.12.
Homologues: Orthologues: chimpanzee MCHR1 (99% identical), macaque MCHR1 (99% identical), pig MCHR1 (97% identical), dog MCHR1 (97% identical), guinea pig MCHR1 (96% identical), mouse Mchr1 (96% identical), rat Mchr1 (96% identical), rabbit MCHR1 (95% identical), tropical clawed frog mchr1.2 (62% identical), zebrafish mchr1b (52% identical), zebrafish mchr1a (47% identical). Paralogues in human: MCHR2 (32% identical), PROKR2 (22% identical), NPY2R (22% identical), PROKR1 (22% identical), GPR19 (22% identical), GPR50 (22% identical), MTNR1A (21% identical), NPY1R (21% identical), TACR1 (21% identical), MTNR1B (21% identical), TACR2 (21% identical), TACR3 (21% identical), and 21 more.
Diseases named in the same sentence as MCHR1 in open-access papers:
MCHR1 is named in the same sentence as 60 diseases in open-access papers, as found by Europe PMC text mining. Sharing a sentence is not in itself a finding about the gene and the disease. The quoted sentences say what the papers report.
Obesity (43 papers, 2011 to 2025). Accumulation of substantial excess body fat. "Six genes (CNR2, DPP4, GLP1R, SLC5A1, HTR2C, MCHR1) that encode therapeutic targets in development of type 2 diabetes or obesity." (PMID 36902588, 2023). "Based on an anorexic effect of the MCH peptide and the lean phenotypes of the MCH-deficient and MCHR1-deficient mice, MCHR1 antagonists have been recognized as attractive targets for the treatment of obesity." (PMID 24924345, 2014). "Although an association of an MCHR1 haplotype (SNPs rs133072 and rs133073) with obesity was observed in two cohorts of German children and adolescents, it was not confirmed in five independent cohorts." (PMID 23626585, 2013). "Our preliminary data from the cynomolgus monkey study showed an association of antagonism of MCHR1 with a downtrend in several obesity-related parameters." (PMID 25505557, 2013). "In an association study, among 106 subjects with severe early onset obesity and a history of hyperphagia, two missense variants were found in MCHR1: Y181H and R248Q." (PMID 23626585, 2013). "Mchr1-deficient (Mchr1−/−) mice have a significantly elevated energy expenditure and show hyperactivity and resistance to diet-induced obesity." (PMID 21637341, 2011). "Here, we report the methylation analysis of a CpG island in the first exon of MCHR1, a gene involved in the control of energy metabolism and linked to obesity in rodents and humans." (PMID 21637341, 2011). "Deletion of MCHR1 creates a phenotype of weight loss and resistance to diet-induced obesity characterized by hyperphagia, hyperactivity, and hypermetabolism, and indicates a central role of MCHR1 in stimulating food intake and increasing body weight in rodents." (PMID 35311242, 2022). "Furthermore, MCHR1-deficient mice exhibit a lean phenotype and resistance to high-fat diet-induced obesity." (PMID 24924345, 2014). "A suggestion implicit in the authors’ findings is that the GPCR trafficking defects into the neuronal cilia, especially Mchr1, could underlie the obesity phenotype in the tubby mice." (PMID 23351214, 2013). "Here, we studied whether DNA methylation in this sequence context may contribute to population- and age-specific effects of MCHR1 alleles in obesity." (PMID 21637341, 2011). "To date, however, only genetic variants of unknown significance and single nucleotide polymorphisms have been identified in PMCH, MCHR1, and MCHR2 to be associated with obesity in humans, although 2 inactivating MCHR1 mutations have been identified in underweight individuals." (PMID 38019584, 2024). "Recently, loss of MCHR1 localization to primary cilia has been linked to the severe obesity seen with Bardet-Biedl syndrome, suggesting that regulation of MCH signaling plays an important role in energy homeostasis and that this pathway could become a pharmacological target to curb appetite." (PMID 24348551, 2013). "MCHR1 mediated signaling in the hypothalamus regulates food intake and energy homeostasis, and the disruption of its normal localization in the cilia could underlie at least in part the obesity phenotype of the tubby mice." (PMID 23351594, 2012). "That implies that the association of MCHR1 and human obesity may be mediated epigenetically." (PMID 21637341, 2011). "Although MCHR1 antagonists have demonstrated efficacy in mouse models of obesity, their performance in clinical trials has been less remarkable." (PMID 38654385, 2024). "Research in recent decades has extensively explored the role of MCH in regulating appetite, sleep, and energy expenditure, spurring studies into MCHR1 as a potential target for obesity therapies." (PMID 38654385, 2024). "We were surprised to find that our analysis revealed that MCHR1 ciliary localization remained largely fixed across males and females, on fasting and diet-induced obesity, with only subtle significant changes observed in cilia length." (PMID 36849261, 2023).
Obesity (continued). "Nearly all of the rather substantial effort devoted to MCH-based drug development has been directed toward producing MCHR1 antagonists with a clinical application in obesity, though several peptide MCHR1 agonists have also been identified." (PMID 36177357, 2022). "Some MCHR1 antagonists which were originally developed for use in obesity have since been considered for alternative clinical applications [e.g., Alb-127158(a) for irritable bowel disease]—though no such trials have yet commenced." (PMID 36177357, 2022). "Extensive efforts have focused on developing MCHR1 antagonists for use in obesity, however, few of these drugs have advanced to clinical trials, and none have gained regulatory approval." (PMID 36177357, 2022). "In preclinical studies involving rodent models of diet-induced obesity, chronic treatment with MCHR1 antagonists resulted in reductions in body weight most commonly in the single or low-double digit percentages." (PMID 36177357, 2022). "The melanin concentrating hormone receptor-1 (MCH-R1) is a promising target in the treatment of obesity." (PMID 36355476, 2022). "When MCHR1 is distributed in the peripheral tissues of mice, it affects the synthesis of fat and is related to obesity." (PMID 32703156, 2020). "Several encouraging pre‐clinical results highlight the melanin‐concentrating hormone receptor 1 (MCHR1) as promising target for anti‐obesity drug development." (PMID 32329245, 2020). "The melanin‐concentrating hormone receptor 1 (MCHR1) is a well characterized target for potential obesity treatment." (PMID 32329245, 2020). "Hyper-methylation of Leptin receptor, melanin-concentrating hormone receptor 1 (MCHR1), and proopiomelanocortin (POMC) was also related to an increase in body mass index (BMI) and a higher risk of obesity, also modifying energy homeostasis in the offspring." (PMID 33042925, 2020). "Several rodent models of obesity showed encouraging results in knock‐out experiments or in administration of MCHR1 antagonists." (PMID 32329245, 2020). "In a diet-induced obesity mouse model it was shown that the anti-obesity effects of the tested MCHR1 antagonist are not only due to suppression of feeding, but also to a stimulation of energy expenditure." (PMID 31244769, 2019). "In the last decade, several MCHR1 antagonists were presented; some have entered clinical trials for the treatment of obesity or are discussed to become anti-diabetic drugs." (PMID 29948643, 2019). "The in vivo quantification of MCHR1 pharmacology is a crucial step for the better understanding of the pathogenesis of a variety of endocrine disorders like obesity, diabetes and insulin resistance." (PMID 28808288, 2017). "Involvement of MCHR1 was reported in diabetes and obesity, and MCHR1 has also been related to asthmatic seizures, colitis, depression, anxiety and promotion of sleep." (PMID 27033361, 2016). "The melanin-concentrating hormone receptor 1 (MCHR1) plays a key role in energy homeostasis and obesity." (PMID 27033361, 2016). "Specific MCHR1 imaging is of high clinical interest for status monitoring in endocrine pathologies like obesity and diabetes." (PMID 27033361, 2016). "All in all, we anticipate that the knowledge gained from our models will facilitate the design and optimization of novel MCHR1 antagonists as promising anti-obesity agents." (PMID 25257526, 2014). "The current meta-analysis suggests that in addition to the treatment of obesity, possible therapeutic targets of MCHR1 antagonists include anxiety disorder, depressive disorder, hypersomnia, sleepiness, male sexual dysfunction, drug addiction, and hypotension." (PMID 24924345, 2014). "Collectively, these facts indicate that MCHR1 is a crucial regulator of energy homeostasis and suggest the positive role of MCHR1 antagonists as anti-obesity therapeutic agents." (PMID 25257526, 2014).
Obesity (continued). "Studies with MCHR1 knockout mice have shown similar physiological adaptations including an increase in resistance to diet-induced obesity and hyperphagia compared to wild-type mice fed a similar diet." (PMID 24348551, 2013). "The ability of MCHR1 antagonist treatment to improve hepatic steatosis was confirmed in a female model of obesity in which ovariectomized mice were fed a regular chow diet." (PMID 23626585, 2013). "In support of the role of MCH/MCHR1 signaling in the regulation of food intake and energy balance, MCHR1 knockout mice (MCHR1−/−) are lean, have an increased metabolic rate and are resistant to diet-induced obesity." (PMID 25505557, 2013). "On the basis of this information, many pharmaceutical companies have pursued the development of MCHR1 antagonists for the treatment of obesity (for a recent review, see Johansson, 2011)." (PMID 23626585, 2013). "This knowledge has stimulated more than 20 companies to seek MCHR1 selective compounds for the treatment of obesity." (PMID 23626585, 2013). "The usefulness of an MCHR1 antagonist in treating human obesity is being explored by others; an Early Phase I Clinical Trial has seen promising results." (PMID 24348551, 2013). "The majority of studies indicated that the MCHR1 antagonists are effective in different models of obesity in a variety of different rodent strains, due to inhibition of food intake and/or energy expenditure." (PMID 24155742, 2013). "In the author’s opinion, there is, at best, only a modest probability that an MCHR1 antagonist will be developed as a treatment for obesity." (PMID 23626585, 2013). "In the present study, we analyzed DNA methylation with respect to allelic status of SNPs rs133072 and rs133073 of the obesity candidate gene MCHR1." (PMID 21637341, 2011). "Mchr1 antagonists inhibit food intake, reduced consumption of palatable food, and, after chronic administration to rats with diet-induced obesity, resulted in a decrease in body weight." (PMID 21637341, 2011). "Conceivably, this epigenetic regulation contributes to the age- and/or population specific effects reported for MCHR1 in several human obesity studies." (PMID 21637341, 2011). "To determine whether body weight and obesity can influence MCHR1 ciliary localization, we assessed the brains of high-fat diet-induced obese mice." (PMID 36849261, 2023). "Future MCH drug development efforts, whether focused on an application in sleep disorders or on any other functions of the MCH system, will likely need to contend with many of the same issues faced during the development of MCHR1 antagonists for obesity." (PMID 36177357, 2022). "Pharmacological validation of these studies suggests that melanin-concentrating hormone receptor 1 (MCHR1) antagonists that mediate MCH regulation could be used as appetite suppressants for obesity." (PMID 35409167, 2022). "A similar lack of coherence in the association of MCHR1 alleles with human obesity has been observed and attributed to differential methylation altering the function of the allele in question." (PMID 35327363, 2022). "As BAT has become a pharmacological target to treat metabolic diseases, the detection of MCHR1 in BAT may be another component that could help to curb the obesity pandemic." (PMID 33502798, 2021). "Moreover, MCH/MCHR1 is considered to be involved not only in a variety of pathologies, such as diabetes, insulin resistance, gut inflammation, colitis, and obesity, but also in a variety of psychiatric disorders, such as depression and anxiety." (PMID 29948643, 2019). "Several centrally active MCHR1 antagonists have been developed for the treatment of obesity." (PMID 31244769, 2019). "As mentioned, the two pioneer compounds, T-226296 from Takeda (Osaka, Japan) and SNAP-7941 from Synaptic (Gottingen, Germany), represent the starting point of small molecular MCHR1 antagonists and present the pharmacological evidence of the anti-obesity therapeutic utility of MCHR1 antagonists." (PMID 25257526, 2014).
Obesity (continued). "However, possibly due to the existence of more effective therapies as well as less conclusive animal data, development activities related to MCHR1 antagonists within the depression/anxiety indication have always lagged behind obesity." (PMID 25257526, 2014). "We hope that the obtained models and information may help to provide an insight into the interaction mechanism of MCHR1 antagonists and facilitate the design and optimization of novel antagonists as anti-obesity agents." (PMID 25257526, 2014). "MCHR1 antagonising quinazoline derivatives are proved to possess distinct anti-obesity activity." (PMID 23731671, 2013). "Fourth, the role of MCH in human energy homeostasis may not be as significant as its role in rodents, consequently, blockade of MCHR1 would be inherently ineffective as a treatment for obesity." (PMID 23626585, 2013). "A number of MCHR1 antagonists have been developed as potential anti-obesity drugs." (PMID 25505557, 2013). "If confirmed, our current data with AMG 076 would suggest that antagonism of MCHR1 alone may exert a likely moderate anti-obesity effect in monkeys and potentially in humans and combination with therapies targeting other pathways may be needed." (PMID 25505557, 2013). "To date, MCHR1 knockout mice have been reported to exhibit an obesity-prone phenotype." (PMID 24155742, 2013). "Dissecting the downstream effectors of Mchr1 in regulating energy balance could address the conflicting effects of Mchr1 trafficking on obesity." (PMID 23351214, 2013). "Our data obtained in blood of individuals aged between 21 and 78 years – a higher methylation level of MCHR1 associated with the A allele of rs133072 – suggests a protective effect of the A allele rather than an association with obesity." (PMID 21637341, 2011). "Therefore, further analyses of the impact of allele-specific and/or age-dependent epigenetic variations of MCHR1 on human obesity shall include adipose tissue available after lipectomy." (PMID 21637341, 2011). "However, it was quite recently announced (April 2022) that a phase 2 proof-of-concept trial would commence in order to evaluate the use of an MCHR1 antagonist known as RGH-076—under development by Gedeon Richter Plc.—as a treatment for hyperphagia/obesity in Prader-Willi syndrome." (PMID 36177357, 2022). "Thus, in the simplest model, Mchr1 trafficking defect to the cilia should mirror its effect on energy balance and cause leanness, rather than obesity, as evident in the tubby mouse." (PMID 23351214, 2013). "Thus, a lower level of Mchr1 protein leads to a protection against obesity in rodents." (PMID 21637341, 2011). "Melanin-concentrating hormone receptor 1 (MCHR1) has been a target for appetite suppressants, which are helpful in treating obesity." (PMID 35409167, 2022). "The melanin-concentrating hormone receptor 1 (MCHR1), which is highly expressed in the lateral hypothalamus, plays a key role in energy homeostasis, obesity and other endocrine diseases." (PMID 27033361, 2016). "Melanin concentrating hormone receptor 1 (MCHR1), a crucial regulator of energy homeostasis involved in the control of feeding and energy metabolism, is a promising target for treatment of obesity." (PMID 25257526, 2014). "Cynomolgus monkey expresses both MCHR1 and MCHR2 and some become obese with age and a sedentary lifestyle, with parallels to human obesity." (PMID 25505557, 2013). "In this article, we describe results of evaluation of AMG 076, a potent and selective small molecule antagonist of MCHR1, in rodent and NHP models of obesity." (PMID 25505557, 2013). "Obesity did not influence cilia frequency, length, or MCHR1 fluorescence intensity in the ARC, PVN, or accumbens." (PMID 36849261, 2023). "The presence of MCHR1 in BAT emphasizes the role of BAT in energy homeostasis and may help uncover treatment approaches for obesity." (PMID 33502798, 2021).